IL6R (interleukin 6 receptor)
Diseases named in the same sentence as IL6R in open-access papers (continued):
Sharing a sentence is not in itself a finding about the gene and the disease.
multiple myeloma (33 papers, 2006 to 2026). "Consistent with a previous report on multiple myeloma plasma cells, there was a significant increase of ds-IL6R expression in carriers of the 358Ala allele (P = 8.3×10−22)." (PMID 23593036, 2013). "The SNP IL6R-rs7529229, in linkage disequilibrium with IL6R-rs8192284, has also been related to risk of multiple myeloma." (PMID 24391818, 2013). "In vivo, IL-6R is expressed on the surface of myeloma cells and released into the serum to become a soluble form (sIL-6R)." (PMID 37823051, 2023). "It is well known that Interleukin-6 (IL-6) is the main growth factor of human myeloma cells, which acts through its receptor IL-6R." (PMID 37823051, 2023). "IL-6R messenger RNA expression was significantly higher in human myeloma cell lines (p < 0.001) compared to other hematopoietic and lymphatic tumors as well as other cancers." (PMID 33414408, 2021). "A recent study found another novel mechanism for metformin to block the IL-6 signaling pathway by decreasing IL-6R expression on multiple myeloma cells." (PMID 34881181, 2021). "The interaction between IL-6 and IL-6R was shown to induce antiapoptotic effects on human esophageal carcinoma and multiple myeloma through the phosphorylation of gp130 and STAT3." (PMID 31252615, 2019). "IL-6 binds to the sIL-6R receptor (IL-6R) on the myeloma cell surface and induces dimerization of gp130 chains, then results in activation of the associated Janus kinase (JAKs)." (PMID 25865044, 2015). "BMSCs stimulate MAPK signaling in myeloma cells through IL-6R-independent mechanisms thereby circumventing the need for Stat3-mediated signaling in response to IL-6 for myeloma cell survival." (PMID 20204067, 2010). "Moreover, in multiple myeloma, copy number amplification of chromosome 1q21, which contains both ADAR1 and interleukin-6 receptor (IL-6R) gene loci, is associated with a poor prognosis, while ADAR1 knockdown alters sensitivity to lenalidomide." (PMID 41020880, 2025). "Moreover, myeloma cell lines that express the IL-6R respond positively to induction of IL-6R signaling, with increased proliferation and reduced apoptosis." (PMID 37744361, 2023). "Intriguingly, IL-6R can serve as a biomarker for metformin action in multiple myeloma." (PMID 33531904, 2021). "However, IL-6 and IL-6R antibodies can block CSF3-induced myeloma cell proliferation." (PMID 37250588, 2023). "Research has identified miR-451a as a regulator of the IL6R gene and an activator of the JAK2/STAT3 pathway, which regulates the proliferation and apoptosis of multiple myeloma cells." (PMID 39129166, 2025). "The analysis of the whole transcriptome data revealed different expression levels of several genes, such as JAK1, JAK2, JAK3, RAF, IL6R, NCAM (CD56), WHSC1, MCL1, BCL2, and IGF1, which showed myeloma pathogenesis." (PMID 30079703, 2019). "In human myeloma cells, PKC-δ has also been shown to regulate phorbol ester-induced shedding of the interleukin-6 receptor." (PMID 27313531, 2016). "Inhibition of tumor cell proliferation by SL1026 and SL1033 was demonstrated in U266B1 myeloma, HepG2 hepatoma, and U87MG glioma cells, and the potency of SOMAmer inhibition of IL-6 was equal to or greater than tocilizumab inhibition of IL-6Rα in all cases." (PMID 24415766, 2014). "In multiple myeloma cell lines, AZA reduced IL6-Rα protein levels within 2 hours, and to an equal extent as cycloheximide, consistent with a mechanism involving protein synthesis inhibition." (PMID 20126405, 2010). "CSF3 promoted the proliferation of myeloma cells, although it did not affect the expression of IL-6 and IL-6R, indicating that IL-6 does not mediate the proliferative effects of CSF3." (PMID 37250588, 2023). "Several studies have demonstrated that inhibition of the IL6R/STAT3 pathway with anti-IL6, IL6R antagonists, or JAK-inhibitors induced apoptosis of human myeloma cell lines in vitro and enhanced the antitumor activity of other anti-myeloma drugs in vivo, attenuating chemoresistance." (PMID 34205916, 2021).
multiple myeloma (continued). "However, in small clinical trials regarding cancer, treatment with anti-IL6 or anti-IL6R has shown no clinical effect in patients multiple myeloma, metastatic renal cell cancer and castration-resistant prostate cancer." (PMID 30038723, 2018). "Importantly, stimulation of myeloma cells with IL-6 increased the proportion of CD45RO in the raft fractions, where CD45RO formed a complex with IL-6R, gp130, STAT3 and PKC, that could potentiate the activation of STAT3, PKC and downstream NF-κB." (PMID 25781885, 2015). "In contrast, 15d-PGJ2 and troglitazone did not affect the expression of IL-6R or activation by phosphorylation of the downstream signaling molecules Jak/Stat3, MAPK, and PI3K/Akt in myeloma cells." (PMID 20204067, 2010). "IL6 is essential in multiple myeloma: cell lines that do not produce IL6 require exogenously added IL6, antisense IL6 strongly reduces proliferation and blocking the IL6R signaling pathways induces apoptosis while its constitutive activation confers resistance to apoptosis." (PMID 34359576, 2021).
colon carcinoma (29 papers, 2010 to 2024). "The colon-cancer associated point mutation within the cytoplasmic domain (R725H) also exhibits diminished IL-6R shedding (~25% reduction)." (PMID 31060243, 2019). "This study has also highlighted the need for investigation of IL6/IL6R-targeted therapies as novel treatment strategies for patients with colon cancer." (PMID 39766336, 2024). "Several targeted drugs display antiangiogenesis effect in colon cancer, such as regorafenib, anti-interleukin-6 receptor antibody, and SARI." (PMID 35747126, 2022). "After controlling for multiple comparisons, authors found that single nucleotide polymorphisms (SNPs) from four genes, IL3, IL6R, IL8, IL15, were associated with increased colon cancer risk." (PMID 34753514, 2021). "Matjaz R. suggested that the IL-6R/STAT3/miR-34a feedback loop promotes colon cancer metastasis by inducing EMT." (PMID 32358527, 2020). "Prostate, breast, and colon cancer cells release high levels of IL-6 and also express the IL-6R/gp80 and gp130 receptor subunits." (PMID 29890702, 2018). "In vivo experiments on wild-type mice have shown that IL-6 is significantly augmented at the colonic tumor environment, and the growth of colon tumors was suppressed when the mice were treated with antibodies against IL6R." (PMID 26321888, 2015). "Soluble form of IL-6R was secreted from the colon cancer cell line itself, and sIL-6R secretion was upregulated by IL-1β stimulation." (PMID 20823887, 2010). "Recent studies have reported an increase in interleukin-6 (IL-6) and soluble interleukin-6 receptor (sIL-6R) levels in the sera of patients affected by colon cancer that correlate with the tumor size, suggesting a potential role for IL-6 in colon cancer progression." (PMID 33923292, 2021). "The role of ADAM17 in colon cancer is thought to be linked to ADAM17-mediated shedding of EGF-R activating ligands, as well as IL-6 trans-signaling, which is also promoted by ADAM17 via the shedding of IL-6R." (PMID 33143292, 2020). "Overall, our data indicate that colon cancer-associated ADAM17 variants (E319G, E406X, M435I) exhibit diminished substrate recognition and/or enzymatic activity towards physiological substrates of the metalloprotease (TNFα, IL-6R, AREG)." (PMID 33143292, 2020). "We therefore speculated that IL-6 trans-signaling initiated by the EGF-R mediated IL-6 secretion and the ADAM17-mediated IL-6R shedding might contribute to colon cancer formation in the APCmin/+ model." (PMID 31694340, 2019). "Furthermore, both LS174T and SW480 colon cancer cell lines were confirmed to be responsive to IL-6: evidenced by the induction of IL-6 responsive genes, and expression of IL-6 receptors (gp130 & IL-6R)." (PMID 28819304, 2017). "We confirmed that colon carcinoma cell lines express IL-6 and IL-6R." (PMID 26673628, 2015). "Many cancer cells, including e.g. prostate, breast, and colon cancer or melanoma, may produce large amounts of IL-6 and express the IL-6R/gp80 and gp130 receptor subunits, which allow them to respond to IL-6 stimulation even in an autocrine manner." (PMID 23517603, 2013). "IL-6 is also involved in signaling and immunoregulatory cascades by binding to its receptor (IL-6R) on gp130-positive cells – thereby activating the transcription factor signal transducer and activators of transcription 3 (STAT3) and increasing the risk of colon cancer." (PMID 36792680, 2023). "The activation of IL-6 trans-signaling by metalloproteinases has been described during colon cancer progression and metastasis, involving a shift from membrane-bound interleukin-6 receptor (IL-6R) expression on the tumor cell surface toward the release of soluble IL-6R." (PMID 33923292, 2021). "Recent reports have shown that aurora kinase A (AURKA), IL6R, NUPR1, and DICER1 play important role in the development, progression, and metastasis of a variety of cancers including colon cancer." (PMID 36685857, 2022).
colon carcinoma (continued). "The expression of GP130, IL-11, IL-11 receptor α (IL-11Rα), IL-6, IL-6 receptor (IL-6R) and STAT3 activation were examined by western blot in DLD-1, HCT-15, and HCT-116 colon cancer cell lines." (PMID 30736824, 2019). "Furthermore, significant positive correlations of CBX4 with STAT1 and IL-6R/STAT3 were observed, and the activation of STAT1 and IL-6/STAT3 signaling has been reported to promote immunosuppression in the TME of colon cancer." (PMID 34222240, 2021). "Estrogen receptor α (ER-α) and IL-6R could not be detected in these three colon cancer cells." (PMID 30736824, 2019).
lung carcinoma (28 papers, 2009 to 2025). "Interestingly, despite its tissue restriction in normal tissue, IL-6Rα has been detected in lung cancer cells and is associated with the EMT/cancer stem cell phenotype." (PMID 31741710, 2019). "Clinically, tocilizumab, a humanized monoclonal antibody targeting IL-6R, has improved symptoms and prognosis in cachectic patients, with Phase II trials in lung cancer confirming its ability to alleviate anorexia and weight loss." (PMID 40704145, 2025). "Our findings represent the first demonstration of the ability of MH to act as an antagonist of a key pro-oncogenic pathway through binding to the IL-6Rα protein expressed by human breast and lung cancer cells." (PMID 31491838, 2019). "Recently, tocilizumab, a humanized recombinant mAb against the IL-6R, showed the potential to improve prognosis in IL-6-expressing lung cancer and recurrent epithelial ovarian cancer." (PMID 30083161, 2018). "In summary, miR-218 is capable to inhibit lung cancer cell proliferation and invasion, at least partially through repressing IL-6R and JAK3 genes expression." (PMID 28830450, 2017). "Additionally, a limited number of advanced lung cancer patients treated with neutralizing antibodies against IL‐6 or its receptor (IL‐6R) experienced amelioration of cachexia‐related symptoms." (PMID 39764565, 2025). "Similarly, a case study involving the treatment of a cachectic advanced lung cancer patient with the anti‐IL‐6R monoclonal antibody tocilizumab resulted in significant weight gain, yet tumor growth continued unabated, leading to subsequent metastases." (PMID 39764565, 2025). "Furthermore, soluble interleukin-6 receptor (sIL-6R) had a significant association with lung cancer risk among never-smoking Chinese women (OR [95% CI]: 2.37 [1.40–4.02])." (PMID 38067398, 2023). "Regarding lung cancer, blocking of IL-6 trans-signaling using sgp130Fc—which is a fusion protein of sgp130 and the crystallizable fragment of immunoglobulin G1—or the anti-IL-6R monoclonal antibodies 1F7 and 25F10, ameliorated tumourigenesis in the oncogenic KrasG12D-induced LAC mouse model." (PMID 31438559, 2019). "Hence, suppressed interleukin-6 receptor could reduce the proliferation of H460 cells for lung cancer therapeutics." (PMID 29254155, 2017). "The positive mode has marker traits pulmonary function and the C-reactive protein, and the few markers genes (IL6R, ARHGAP10, BCL7B, PABPC4) are also involved in immune response and lung cancer progression." (PMID 34157017, 2021). "Several studies have shown that the estrogen receptor beta (ESR2) appeared in many tumors, including lung cancer, wherein ESR2 and interleukin 6 receptor (IL-6R) interacts to mediate lung cancer progression." (PMID 34497656, 2021). "Similarly, in lung cancer, afatinib-induced STAT3 activation reduces drug sensitivity, which can be reversed by inhibiting IL-6R/JAK1/STAT3 signaling." (PMID 40999385, 2025). "disclosed that in lung cancer, ERO1L promotes IL6R secretion to activate the NF-κB pathway, leading to an upregulation of MUC16 gene expression, and the C-terminal of MUC16 further fosters the EMT phenotype and IL6 release, creating a positive feedback loop that exacerbates lung cancer progression." (PMID 38361923, 2024). "The newly-identified miR-218–mediated IL-6R and JAK3 genes silencing may facilitate a better understanding of the molecular mechanisms of lung cancer progression and present a new strategy to treat patients with lung cancer." (PMID 28830450, 2017). "In order to correlate our findings with lung cancer prognosis in clinical settings, we analyzed the data from 1405 lung cancer patients and the gene expression of miR-218 host genes (SLIT2/SLIT3), IL-6, IL-6R, JAK3 and STAT3 in their tumor tissues." (PMID 28830450, 2017).
lung carcinoma (continued). "Moreover, mutations in EGFR kinase domain have been shown to mediate STAT3 activation by IL-6 production in human lung carcinomas, suggesting that EGFR-like STAT3 activation can be mediated by IL-6R or GP130 receptors in an autocrine manner." (PMID 19088723, 2009). "We further observed that ALDH1A1 positive cells had higher levels of IL-6R, JAK3 and phosphorylated STAT3, suggesting that the lower levels of miR-218 may be responsible for the upregulation of STAT3 signaling in ALDH positive lung cancer cells." (PMID 28830450, 2017).
juvenile idiopathic arthritis (27 papers, 2013 to 2026). Juvenile idiopathic arthritis (JIA) is the term used to describe a group of inflammatory articular disorders of unknown cause that begin before the age of 16 and last over 6 weeks. "In our series (Table A1), other observed risk factors were juvenile rheumatoid arthritis under immunosuppressive treatment (methotrexate, prednisone, and an interleukin-6 receptor blocker) and Crohn’s disease (on a tumor necrosis factor-alpha blocker)." (PMID 38920894, 2024). "Various clinical trials have demonstrated the superior efficacy of the IL6R monoclonal antibody, which is currently authorized for treating RA and juvenile idiopathic arthritis." (PMID 38835791, 2024). "Initially used for treatment of RA, the anti-IL-6R antibody Tocilizumab has since been successfully approved for therapy of systemic juvenile idiopathic arthritis and polyarticular juvenile idiopathic arthritis." (PMID 34347128, 2022). "Tocilizumab is an IL-6R blocking agent currently approved for the treatment of both systemic and polyarticular juvenile idiopathic arthritis in children above 2 years of age." (PMID 34123970, 2021). "As the anti-IL-6R antibody is already an approved treatment for children with systemic juvenile idiopathic arthritis, it is potentially applicable as a treatment for children with DMD." (PMID 29078808, 2017). "This study presents effects of intravenous laser blood irradiation (ILBI) in a transient immunodeficiency patient with juvenile idiopathic arthritis (JIA) treated with an interleukin-6 receptor inhibitor (Tocilizumab)." (PMID 24715926, 2014). "The immunogenicity of influenza vaccine was recently investigated in 27 patients with systemic-onset juvenile idiopathic arthritis receiving tocilizumab, an anti-interleukin-6 receptor antibody." (PMID 23510667, 2013). "However, most of these reports derived from juvenile arthritis published before interleukin-1 or interleukin-6 receptor antagonists became available." (PMID 40830237, 2025). "Efficacy and safety of tocilizumab (TCZ), an interleukin-6 receptor inhibitor, were demonstrated in juvenile idiopathic arthritis (JIA) with polyarticular course (pJIA) in the CHERISH trial." (PMID 29654485, 2018). "Tocilizumab, humanized anti-IL-6 receptor (IL-6R) monoclonal antibody, is highly efficacious for the treatment of intractable autoimmune inflammatory diseases, including RA and juvenile idiopathic arthritis (JIA) in clinical trials." (PMID 30884802, 2019).